IGBP1P5 (IGBP1 pseudogene 5)
Gene: Processed pseudogene on chromosome 4 (27,585,145 to 27,586,144, forward strand). Ensembl gene ENSG00000250858.
Diseases named in the same sentence as IGBP1P5 in open-access papers:
IGBP1P5 is named in the same sentence as 2 diseases in open-access papers, as found by Europe PMC text mining. Sharing a sentence is not in itself a finding about the gene and the disease. The quoted sentences say what the papers report.
Patent ductus arteriosus (1 paper, 2024). In utero, the ductus arteriosus (DA) serves to divert ventricular output away from the lungs and toward the placenta by connecting the main pulmonary artery to the descending aorta. "The Human Phenotype Ontology (HBO) project shows IGBP1, the parent gene of IGBP1P5, is related to ventricular septal defect and patent ductus arteriosus." (PMID 39872005, 2024).
IGBP1P5 also shares sentences with these, for which no sentence is quoted: ventricular septal defect (1 paper).